OASL (2'-5'-oligoadenylate synthetase like)
Description:
Does not have 2'-5'-OAS activity, but can bind double-stranded RNA. Displays antiviral activity against encephalomyocarditis virus (EMCV) and hepatitis C virus (HCV) via an alternative antiviral pathway independent of RNase L.
Synonyms: TRIP-14; p59OASL; TRIP14; OASL1; OASLd; p59 OASL; p59-OASL
Tractability: PROTAC: ubiquitination databases record sites on it; its protein half-life has been measured.
Gene: Protein-coding gene on chromosome 12 (121,017,763 to 121,039,246, reverse strand). Ensembl gene ENSG00000135114.
Subcellular location: Nucleus, nucleolus (Isoform p56); Cytoplasm; Cytoplasm (Isoform p30)
Subcellular location (Human Protein Atlas): Cytosol; Nucleoplasm
Pathways (Reactome):
Immune System: Interferon alpha/beta signaling; Interferon gamma signaling; OAS antiviral response
Gene Ontology:
Molecular function: 2'-5'-oligoadenylate synthetase activity; DNA binding; double-stranded RNA binding; protein binding; RNA binding; nuclear thyroid hormone receptor binding; nucleotidyltransferase activity
Biological process: defense response to virus; interleukin-27-mediated signaling pathway; negative regulation of viral genome replication; positive regulation of RIG-I signaling pathway; response to virus; antiviral innate immune response; type I interferon-mediated signaling pathway; defense response
Cellular component: cytoplasm; cytosol; membrane; nucleolus; nucleoplasm
Genetic constraint (gnomAD): Loss-of-function variants: 29 observed, 37.71 expected, observed/expected ratio (o/e) 0.77, 90% interval 0.57 to 1.05. The upper end of that interval is the gene's LOEUF score, 1.05, which puts it in group 4 of 6, group 1 being the genes least tolerant of losing a copy. Missense variants: 620 observed, 666.86 expected, observed/expected ratio (o/e) 0.93, 90% interval 0.87 to 0.99. Synonymous variants: 252 observed, 268.57 expected, observed/expected ratio (o/e) 0.94, 90% interval 0.85 to 1.04.
Homologues: Orthologues: chimpanzee OASL (98% identical), macaque OASL (93% identical), rabbit OASL (74% identical), guinea pig OASL (73% identical), rat Oasl (73% identical), mouse Oasl1 (70% identical), pig OASL (42% identical). Paralogues in human: OAS1 (28% identical), OAS3 (27% identical), OAS2 (24% identical).
Diseases named in the same sentence as OASL in open-access papers:
OASL is named in the same sentence as 92 diseases in open-access papers, as found by Europe PMC text mining. Sharing a sentence is not in itself a finding about the gene and the disease. The quoted sentences say what the papers report.
viral infection (76 papers, 2009 to 2026). "As a member of the OAS protein family, OASL is associated with the innate immune defense against viral infections." (PMID 34335699, 2021). "Genes specifically associated with defense against viral infections, such as OASL, were also strongly up‐regulated." (PMID 28360091, 2017). "This research explores the structural and functional consequences of high-impact missense variants in three immune-related genes MMP8 (D253N, Y261S), GZMK (A42P, L122P), and OASL (W216C) with possible relevance to host response in epidemic viral infections." (PMID 41807577, 2026). "Another OAS homolog, OASL, has dual functions that depend on the phase of viral infection and various mechanisms and is postulated to interfere with the 2–5 A and RNase L pathway." (PMID 38932231, 2024). "The induction of OAS1, OAS2, and OASL, which, as main sensors for viral infections, explains the induction of numerous interferon-induced proteins (e.g., IFIT1, IFIT2, IFI44, MX1, MX2)." (PMID 39062793, 2024). "OASL is a crucial factor in the activation of type I IFNs and it was acknowledged as the product induced by virus infection, but many studies revealed the elevated expression of OASL during bacterial infection." (PMID 39091676, 2024). "After the onset of viral infection and stimulation of OASL expression in infected and surrounding cells, OASL connects and activates RIG-I by simulating pUb, further increasing the expression of IFN." (PMID 37922302, 2023). "The role of OASL gained significant attention in studies on innate and adaptive immune responses and it is considered to have a dual function in viral infection." (PMID 37209263, 2023). "Viral infections generated IFNs, which were accompanied by the transcription of OASL, and activated IFN responsive pathways after upregulating IFN regulated genes including OAS1 and STAT1." (PMID 36765396, 2023). "Amongst the genes with the most significant difference in expression between the WT and mutant virus infections were antiviral genes (e.g., IRF1, IFIT2, OASL) that exhibited a higher expression in the WT virus infection." (PMID 37243147, 2023). "These contentious findings prompt further investigation of the precise role of OASL during virus infections." (PMID 36604592, 2023). "OASL is essential to fight viral infections in the innate and adaptive immune responses, usually via IFN signaling, and has recently been shown to be a biomarker or predictor of therapeutic responses in autoimmune diseases." (PMID 35183246, 2022). "Among all differentially expressed genes, two upregulated genes, RAD2 and OASL, known to be rapidly induced in response to viral infection, were observed." (PMID 34361973, 2021). "It was worthy of noting the expressions of OASL triggered by various viruses were different enough to tell influenza infection apart from other viral infections." (PMID 32714913, 2020). "The top-scoring genes in the network include the members of Interferon Induced Transmembrane Proteins (IFITM1 and IFITM3) followed by MT1E, MT1X, and MT1G and OASL, all essential proteins involved in the innate immune response to viral infection." (PMID 32012164, 2020). "Upon initial viral infection and OASL induction as an ISG in response to IFN signaling, OASL bound to RIG-I and mimicked K63-linked ubiquitin." (PMID 32012730, 2020). "OASL, a member of the OAS protein family, like APOBEC1, is associated to the innate immune defense against viral infections." (PMID 32545414, 2020). "We cloned chicken MX1, IFI6, IFIT5, RSAD2, and OASL into eukaryotic expression vector and evaluated their effects on virus infection in DF1 cells." (PMID 32183248, 2020). "The mRNA expression levels of IL-1β, IL-6, IL-8, IFNs, TNF-α, Mx, and OASL were significantly upregulated during the viral infection." (PMID 31288442, 2019).
viral infection (continued). "While OASL is an interferon-induced protein that regulates the early phase of viral infection, proviral functions like enhancement of viral persistence are also associated with members of the OAS family." (PMID 30651403, 2019). "It has been shown that OASL is rapidly induced upon viral infection through interferon regulatory factor 3 (IRF3), as well as IFN signaling, and that CSFV Npro interacts with IRF3 and induces its proteasomal degradation to prevent type I IFN induction." (PMID 28331099, 2017). "OASL was identified to be strongly induced following viral infection through engaging the RNA sensor RIG-I and increasing signaling through this pathway to enhance the anti-viral type I IFN response." (PMID 28580319, 2017). "Goose OASL may inhibit viral infection through RNase L-dependent signaling or control viral infection through RIG-dependent signaling." (PMID 39518785, 2024). "OASL is strongly induced upon viral infection to enhance the antiviral IFN response." (PMID 38162574, 2023). "This trend follows for the other ISG transcripts analyzed, with ISG15 having an approximately 7.1-fold increase, IFIT1 an 11.7-fold increase, and OASL a 13.2-fold increase in transcripts in the C7/10-derived virus infection compared to the BHK-derived virus infection." (PMID 37632027, 2023). "Both the in vitro phase-separation assays and the virus infection study collectively show that OASL drives the condensation of RIPK3 and ZBP1 by recruiting them into its liquid droplets via protein–protein interactions, which ultimately induces RIPK3 autophosphorylation." (PMID 36604592, 2023). "We detected duck IFN-β and ISGs (Mx, OASL) production under viral infection." (PMID 35303942, 2022). "OASL is also a member of ISGs and induced by virus infection rapidly via IFN signaling." (PMID 34064193, 2021). "We, therefore, asked whether OASL enhances the activation of OAS/RNase L signaling to prevent viral infection." (PMID 29973937, 2018). "Interestingly, DF1dOASL+/+ and DF1dRIG-I+/+ cells showed comparatively lower levels of DK/49 and GS/65 virus titers compared to DF1 cells expressing empty vectors, supporting that duck OASL can efficiently prevent viral infection, similarly to duck RIG-I." (PMID 29973937, 2018). "Likewise, the availability of cytosolic viral dsRNA during virus infection may determine the duration and frequency of OASL LLPS." (PMID 36604592, 2023). "Finally, OASL (oligoadenylate synthase-like protein) another interferon induced gene upregulated by BG treatment is a key antiviral factor that regulates early phase of viral infection by degrading viral RNA." (PMID 35386334, 2022). "OASL is induced by multiple viral infections in chicken, and studies of WNV infection with recombinant chicken OASL indicate flavivirus-targeted host-restriction activity." (PMID 38675911, 2024). "Previous studies have identified that following viral infection, type I IFN signaling induces the production of the OAS family consisting of OAS1, OAS2, OAS3, and OAS-like (OASL) protein." (PMID 38650851, 2024). "Their findings suggest that OASL behaves like an antiviral gene, providing new insights into the roles of the OAS gene family members in the immune response to viral infections." (PMID 39282474, 2024). "2′-5′-oligoadenylate synthetase-like (OASL) and myxovirus resistance 1 (MX1) are two of the most induced proteins in cells following IFN-I or viral infection." (PMID 36537793, 2023). "Our study revealed that OASL undergoes dsRNA-dependent LLPS, which serves as a scaffold to facilitate the assembly of the RIPK3–ZBP1 necrosome during virus infection." (PMID 36604592, 2023). "For example, upregulated genes OASL, OAS1, OAS2, and OAS3 belong to the OAS family, a group of antiviral enzymes induced by type I IFNs, which can locate and bind viral dsRNA after viral infection." (PMID 36655136, 2023). "Viral infections lead to synthesis of IFN and IRF3, and these proteins lead to transcription of OASL." (PMID 37922302, 2023).
viral infection (continued). "It has been reported that interferon can significantly trigger the production of many interferon-induced genes (IFIT1, IFITM3, MX-1, OASL, ISG15, PKR, GBP1, Viperin, BST2, IRF-1, and CXCL10), which play key roles in the resistance to viral infection." (PMID 36337195, 2022). "DPV CHv-BAC-G-ΔUL41 mutant virus infection induced more duck IFN-β and ISGs (Mx, OASL) production than infection with the DPV CHv-BAC parent virus." (PMID 35303942, 2022). "Studies have found that OASL makes the RNA detection system based on RIG-I more sensitive to viral RNA, which can be activated under viral infections that are relatively below the threshold level, and the SARS-Cov-2 virus in the body can be found faster." (PMID 34920753, 2021). "CCL2, a type I IFN receptor-mediated chemoattractant that promotes monocyte migration to the site of infection, and OASL, a type I IFN-induced gene, had higher expression in patients with mild viral infection." (PMID 33765435, 2021). "OASL is an interferon stimulated gene (ISG) that is directly and rapidly induced upon viral infection." (PMID 34442377, 2021). "OASL and SAMD9L have been shown to be important in viral infection and innate immunity, but the mechanism of their action is different from that of ISG15." (PMID 34920753, 2021). "This dataset included some genes with known antiviral functions, such as APOBEC3A and OASL, which is potentially relevant for the inability of patients with high endogenous ISG levels to spontaneously clear the viral infection." (PMID 28360091, 2017). "Previous work has identified that following viral infection, type I IFN signaling induces the production of the 2′-5′-oligoadenylate synthetase (OAS) family, which include OAS1, OAS2, OAS3, and OAS-like (OASL) protein." (PMID 28580319, 2017). "We found 12 downregulated genes involved in immune response and the immune response to virus infection, and interestingly, they were mainly related to the interferon family of anti-viral factors, such as IFIT1, IFIT3, and OASL." (PMID 22455445, 2012). "Moreover, previous studies have implicatedsimilar ISGs, including OASL, IFI27, IFIT1 and IFI44L, in the pathogenesis of other viral infections such as hepatitis C virus (HCV),suggesting a broader role for these genes in viral-induced liver diseases." (PMID 40322700, 2025). "In the present study, the transcription levels of proinflammatory cytokines and IFNs did not change significantly in the testis after viral infection, but the transcription level of OASL increased significantly." (PMID 36883685, 2023). "In particular, OASL binds to RIG-I and activates and enhances RIG-I signaling; OAS1 binds to viral dsRNA and, together with DDX60, helps RIG-I recognize viral RNA and amplify viral-induced RIG-I-mediated type I IFN expression after viral infection." (PMID 36655136, 2023). "OASL chaperones the assembly of RIPK3 and ZBP1 via liquid-liquid phase separation, which induces RIPK3 and necroptosis activation, thereby modulating inflammation and host defence against viral infection." (PMID 36604592, 2023). "However, during viral infection, the expression of ISGs including DHX58, IFITM3, ISG15, and OASL was upregulated in the livers of WT mice, while Neurl3−/− livers expressed a higher level of proteins related to inflammatory response such as S100A9 and CD47." (PMID 35792897, 2022). "In a previous EPF genome-wide expression study (GWES), several genes involved in the early stages of viral infection were overexpressed in patients with the generalized form of EPF compared to healthy individuals, including IFITM3, APOBEC3A, APOBEC3G, OAS1, OASL, SERINC3, and RPLP2." (PMID 35632621, 2022). "Finally, dSpace analysis identified several genes (CCL2, OASL, CASP7, TMEM123, MAFB, VRK2, UBE2L6, NAPA) higher in patients with mild viral infection than those with severe viral infection or HCs." (PMID 33765435, 2021).
viral infection (continued). "Meanwhile, we found that IFNs could significantly trigger the production of a variety of IFN-induced genes (IFIT1, IFITM3, Mx-1, OASL, ISG15, PKR, GBP1, Viperin, BST2, IRF-1, and CXCL10) and MHC molecules, which play key roles in resistance to virus infection." (PMID 32655518, 2020). "In the upregulated genes in both chMDA5 and poly(I:C) groups, many genes were ISGs, such as MX1, IFI6, IFIT5, RSAD2, OASL, and, CMPK2, which suggested that these genes might play important roles in restricting virus infection in chicken." (PMID 32183248, 2020). "Rather than OASL acting as an antiviral protein as it does during many other viral infections, KSHV appears to have found a way to utilize OASL for its own benefit." (PMID 29499066, 2018). "As expected, although binding dsRNA, dOASL-3K* together with the other two avian OASL mutants (dOASL-3D* and oOASL-3D*) lacked 2–5A activities and did not activate RNase L to degrade rRNA, failing to prevent virus infection in DF1 and DF1OASL−/− cells." (PMID 29973937, 2018). "Three of the genes (ISG15, OASL, IL16) have previously been reported to be associated with host response to viral infection, although they are not entirely specific to such a response." (PMID 28588308, 2017). "A variety of genes such as OAS2, PARP9, OASL, IFIT2, IFI3, CCL8, CXCL10, etc., were highly upregulated and correlated with high viral load, suggesting that innate immune response genes were activated in a viral load dose response manner to control the viral infection." (PMID 37333115, 2023). "For example, 2′-5′-oligoadenylate synthetase like (OASL) and interferon alpha inducible protein 6 (IFI6) were significantly up-regulated in the TC-Infection group at both transcriptome and proteome datasets, which were involved in immune response during virus infection." (PMID 35154273, 2022). "Indeed, CXCL10 was reported to be a key regulator of the cytokine storm in SARS-CoV-2 infection, CXCL1 to play a role in chemotactic neutrophils in bacterial infections, and OASL to be involved in IFN-gamma signaling and PI3K-Akt signaling pathways, which can restrict virus infection." (PMID 34899651, 2021). "To investigate whether the antiviral effect of C11orf83 is through OASs-RNase L system, we examined the expression of OAS family four members (OAS1, OAS2, OAS3, and OASL) at the mRNA level in HEK293 cells that only overexpressed C11orf83 but no viral infection." (PMID 28418037, 2017). "A four-gene blood signature that includes ISG15, IL16, 2′,5′-Oligoadenylate Synthetase Like (OASL), and Adhesion G protein-coupled Receptor E5 (ADGRE5) yielded an AUC of over 0.90 in distinguishing various viral infections from non-viral conditions." (PMID 39861921, 2025). "Notably, we discovered upregulation of multiple ISGs, such as ZBTB16, MX1, OASL, RSAD2, CMPK2, and CXCL14 in the DiMNF treated primary cells, even in the absence of viral infection." (PMID 37672505, 2023).
COVID-19 (23 papers, 2020 to 2026). A disease caused by infection with severe acute respiratory syndrome coronavirus 2. "Similarly, decreased expression of multiple IFN-I-inducible genes including MX1, OAS3 and OASL has been associated with persistent symptoms after COVID-19." (PMID 38532465, 2024). "The association between OASL and TB infection has also been validated, and OASL plays a central role in COVID-19 immunopathogenesis." (PMID 38162574, 2023). "Albeit to a lesser extent, IL-1RAP, OASL and MX1 genes, which belong to the “senescence associated secretory phenotype” (SASP), were also found significantly upregulated in acute COVID-19 vs. HC monocytes." (PMID 34572439, 2021). "Of note, OASL was significantly upregulated in severely affected COVID-19 patients." (PMID 34867933, 2021). "In this study, the highest differentially expressed genes in COVID-19 (+) tissue, including ISG15 itself, IFIT1, RSAD2, OAS1, MX1, OASL, and IFIT3, are all important for the ISG15 pathway’s progression and are part of the lung tissue’s antiviral response." (PMID 38932146, 2024). "The AUC of genes in the COVID-19 cohort are as follows: IFI6, 0.678; IFI27, 0.866; IFI44L, 0.786; OASL, 0.834; RSAD2, 0.770." (PMID 36911695, 2023). "Results demonstrated that OAS1, OAS2, OAS3, and OASL were all highly expressed in SARS-CoV-2 infected NHBE (OAS 1 − 3, P < 0.01) and in the blood leucocytes of COVID-19 patients (all P < 0.001)." (PMID 36949448, 2023). "Important gene combinations in the white blood cells of patients with COVID-19, including IFIT3, OASL, USP18, XAF1, IFI27, and EPSTI1, can be used for its diagnosis." (PMID 35928229, 2022). "In addition, IPIN analysis from COVID-19 patient lung tissue revealed that IFIH1, DDX58, ISG15, OASL, and XAF1 were hub genes in the network." (PMID 35625619, 2022). "Interestingly, given the important role of type I interferon (IFN-I) in COVID-19, we also found decreased expression of multiple IFN-I-inducible genes including MX1, OAS3, and OASL." (PMID 35027067, 2022). "We found an SASP including IL1RAP, OASL and MX1 genes significantly upregulated in acute COVID-19." (PMID 34572439, 2021). "Genes associated with the IFN pathway, such as IFI27, IFIT1, IFIT2, OASL and OAS3, showed significantly higher expression levels, in particular individuals with long COVID-19 when compared to non-long COVID-19 and the organoid systems infected with the alpha variant." (PMID 40055791, 2025). "OASL, RSAD2, ISG20, IFI16, and IFIT1 were not previously annotated in the COVID-19 KEGG pathway." (PMID 38580667, 2024).